RNU6-446P (RNA, U6 small nuclear 446, pseudogene)
Gene: Small nuclear RNA gene on chromosome 17 (62,683,905 to 62,684,010, forward strand). Ensembl gene ENSG00000199697.
Homologues: Orthologues: chimpanzee U6 (100% identical), macaque U6 (84% identical), pig U6 (80% identical), rabbit U6 (80% identical), rat LOC120094862 (79% identical), rabbit U6 (76% identical), rat U6 (74% identical), dog U6 (73% identical), rat LOC120095356 (73% identical), dog U6 (69% identical), mouse Gm22542 (60% identical). Paralogues in human: RNU6-333P (83% identical), RNU6-574P (83% identical), RNU6-1084P (82% identical), RNU6-20P (82% identical), RNU6-38P (82% identical), RNU6-73P (82% identical), RNU6-1249P (81% identical), RNU6-128P (81% identical), RNU6-1316P (81% identical), RNU6-25P (81% identical), RNU6-28P (81% identical), RNU6-29P (81% identical), and 1287 more.